AQP1 (aquaporin 1 (Colton blood group))
Diseases named in the same sentence as AQP1 in open-access papers (continued):
Sharing a sentence is not in itself a finding about the gene and the disease.
glioma (35 papers, 2010 to 2025). A benign or malignant brain and spinal cord tumor that arises from glial cells (astrocytes, oligodendrocytes, ependymal cells). "For instance, insulin-like growth factor binding protein 3 (IGFBP-3), Cullin1 (Cul1), Golgi phosphoprotein 3 (GOLPH3), and aquaporin 1 (AQP1) have all been associated with glioma progression and invasiveness." (PMID 40867240, 2025). "Specifically, AQP1 can increase the proportion of glioma-associated microglia and macrophage infiltration." (PMID 37280594, 2023). "Glioma invasiveness has been linked to AQP1 overexpression, which is greater in migrating cells than in the tumor core." (PMID 32679804, 2020). "Glioma invasiveness has also been linked with AQP1 overexpression." (PMID 38336645, 2024). "Conversely, down-regulation of AQP1 has been associated with the protection of tumors against cytotoxic edema by maintaining extracellular acidification, thereby facilitating the metastasis of glioma (Pedersen, Hoffmann & Mills, 2001)." (PMID 37904849, 2023). "AQP1 may be implicated in glioma formation by interacting with the transcriptional regulation networks involving the FOXO4, MAZ, and E2F1/2." (PMID 38057925, 2023). "In addition, it has been reported that AQP1 up-regulation is associated with angiogenesis in gliomas and is predominantly located perivascularly and in areas of tumor infiltration whereas distant from the tumor center." (PMID 34712604, 2021). "AQP1 overexpression in rat C6 glioma CSCs enhanced cell viability and migration, potentially promoting glioma progression through transcriptional networks involving Foxo4, Maz, and E2F factors." (PMID 40806720, 2025). "Acetazolamide, a carbonic anhydrase inhibitor, was discovered to suppress AQP1 expression, which shielded tumours from cytotoxic oedema by maintaining extracellular acidity and promoted tumour spread in glioma." (PMID 38336645, 2024). "Of special importance is the role of AQP1 and -4 in the proposed mechanism of invasiveness and migration of glioma cells." (PMID 38476871, 2024). "A four-gene signature (ACTN1, AQP1, LAMC3, NRM) prognostic risk model was constructed among the differentially expressed genes (DEGs) identified in the grade II/III gliomas molecular subtypes." (PMID 38307919, 2024). "AQP1, for example, is upregulated in the peritumoral area, especially in the vessels surrounding reactive astrocytes in high-grade gliomas." (PMID 38476871, 2024). "AQP1 overexpression resulted in increased cell viability and cell migration, indicating its functional impact on glioma progression." (PMID 38057925, 2023). "For instance, the expression of AQP1 has been found to correlate with the malignancy grade of gliomas as well as the treatment outcomes of various malignant cancer." (PMID 38057925, 2023). "AQP1 overexpression recombinant vector was introduced into C6 rat glioma cells to construct an AQP1 overexpression C6 cell line, and its effect on cell viability and migration ability was detected by MTT and Transwell." (PMID 38057925, 2023). "For example, AQP1 contributes to the formation of new blood vessels around gliomas, accelerating invasion toward surrounding brain tissues." (PMID 37280594, 2023). "In this study, we aimed to investigate the role of AQP1 in glioma formation by overexpressing it in the C6 glioma cell line." (PMID 38057925, 2023). "To investigate the role of AQP1 in glioma formation, we conducted an experiment where we overexpressed AQP1 in the rat C6 glioma cell line." (PMID 38057925, 2023). "While the precise composition of the C6 glioma cell line in terms of cancer stem cells remains a topic of debate with varying reported percentages, we observed that the overexpression of AQP1 led to increased cell viability and cell migration." (PMID 38057925, 2023). "The enhanced mobility of C6 cells after AQP1 overexpression suggests a transformation from cancer stem cells, which constitute a major portion of the C6 glioma cell line, into invasive cancer cells." (PMID 38057925, 2023).
glioma (continued). "The data presented in this study shed light on the potential involvement of AQP1 in glioma progression and provide insights into the dysregulation of gene expression in glioma." (PMID 38057925, 2023). "Using D54MG glioma cells stably transfected with either AQP1 or AQP4 expression construct, it was further demonstrated that PKC activity regulates water permeability through phosphorylation of AQP4." (PMID 35847914, 2022). "AQP1 is overexpressed in gliomas and peritumoral tissue with its expression level positively correlating to the histological grades of astrocytoma." (PMID 36010640, 2022). "Acetazolamide, carbonic anhydrase inhibitor, was found to inhibit the expression of AQP1, which protected tumor from cytotoxic edema by maintenance of extracellular acidification and promoted tumor metastasis in glioma." (PMID 35847914, 2022). "In this report, using glioma cells stably transfected with either AQP1 or AQP4, it was clearly demonstrated that PKC activity regulates water permeability and that this phenomenon can be modulated by phosphorylation of AQP4." (PMID 35847914, 2022). "Overexpression of the AQP4 in our glioma models of invasion/migration is confirmed by immunohistochemistry in this study, and the overexpression of the AQP1 was also detected in invasion/migration." (PMID 36077717, 2022). "Human glioma cell lines U251 and U87 cells were transfected with either a human AQP1 expression vector or an empty vector (mock) as the control." (PMID 32253832, 2020). "Up-regulation of Aquaporin1 (AQP1) gene has been reported to promote the invasiveness of glioma cells." (PMID 28404978, 2017). "Previous study have pointed out that glioma cells were isolated and grown as cell lines would lose AQP1 expression such as U87 (astrocytoma, WHO grade III), STTG-1 (anaplastic astrocytoma, WHO grade III) and D54 (WHO grade IV)." (PMID 29245912, 2017). "AQP5 have been found expressed highly in primary human glioma cells compared with normal tissue, this is in accordance with the study that reported AQPs (such as AQP1, AQP5 and AQP8) have been observed in high-grade tumors of various tissues." (PMID 28404978, 2017). "We show that hypoxia increases Aqp1 mRNA and protein levels in tissues, namely mouse brain and lung, and in cultured cells, the 9L glioma cell line." (PMID 22174795, 2011). "Oshio and colleagues documented intense AQP1 upregulation in 36 human glial tumours using RT-PCR, Western blotting and immunohistochemistry and demonstrated that AQP1 localization was primarily or exclusively to the membrane of neoplastic astrocytes." (PMID 21119881, 2010). "Owing to the role of molecular markers in the early diagnosis of gliomas, we hypothesized that AQP1 and AQP4, as homeostatic brain proteins, could act as potential anticancer therapeutic targets." (PMID 38476871, 2024). "In this study, we aimed to characterize the expression patterns of genes encoding AQP1 and AQP4 proteins and to identify the genes present in the cancerous microenvironment that potentially regulate or correlate with their expression in human gliomas." (PMID 38476871, 2024). "Our results are supported by these findings, as aquaporin expression patterns increased when compared between molecular subtypes of gliomas: AQP1 is increased in other subtypes of LGG classification (astrocytoma); in contrast, AQP4 is increased in only the classical subtype GBM." (PMID 38476871, 2024). "For example, AQP1 is involved in the formation of peritumoral neovascularization of glioma." (PMID 37280594, 2023). "Similarly, dexamethasone, a commonly used medication for glioma treatment, inhibits C6 cell proliferation mediated by AQP1." (PMID 38057925, 2023). "Through transcriptomic analysis, we identified that AQP1 overexpression may enhance glioma tumorigenesis by influencing the transcriptional regulation networks involving Foxo4, Maz, and E2F families." (PMID 38057925, 2023). "Upregulation of AQP1 has also been related to glioma cell migration." (PMID 36768856, 2023).
glioma (continued). "Increased AQP1 expression has been shown to enhance the invasive capabilities of glioma cells." (PMID 38057925, 2023). "Interestingly, AQP1 expressing glioma cells, by contrast, were completely unaffected by changes in PKC activity." (PMID 35847914, 2022). "AQP4 expressing glioma cells showed significantly reduced invasion compared with AQP1 and S180 expressing tumors as determined by quantitative stereology, consistent with a differential role for AQP1 and AQP4 in this process." (PMID 35847914, 2022). "Dexamethasone, which promotes AQP1 transcription, increases the invasiveness of glioma cells." (PMID 32679804, 2020). "AQP1 overexpression has been observed in diverse types of gliomas, such as glioblastoma, astrocytomas, oligodendrogliomas, ependymomas and glioastrocytomas; the levels of expression have been reported to correlate with the grade of malignancy and invasiveness of the tumors." (PMID 32679804, 2020). "In the discovery process, two particular genes stand out with high hazard ratio (HR) and concordance index (CI) in univariate Cox model, AQP1 (HR = 3.3, p < 0.05, CI = 0.711) and MEOX2 (HR=2.5, p < 0.05, CI = 0.675), both of which are lesser known to be associated with survival in gliomas." (PMID 30626092, 2019). "Accordingly, reintroduction of AQP4 into AQP4-deficient glioma cell lines enhanced cell adhesion rather than cell growth, whereas AQP1 expression led to enhanced cell growth and migration." (PMID 22590566, 2012). "In addition, high AQP4 expression levels are also detectable in well-differentiated low-grade gliomas and there is indication that only the expression of AQP1 enhanced cell growth and migration of gliomas, while AQP4 expression enhanced cell adhesion." (PMID 21548930, 2011). "Endo and colleagues demonstrated AQP1 immunoreactivity in glioma cell lines implanted in rodents." (PMID 21119881, 2010). "Overexpression of AQP4 and AQP1 were assessed in invasion/migration models, highlighting the pathophysiological role of these two aquaporins in water exchange that, in turn, determine the lower values in the observed R1 relaxation rate constant in glioma invasion/migration." (PMID 36077717, 2022). "In addition to the Na+/K+ ATPase, which has been shown to modulate the transmembrane water exchange, the immunohistochemistry (IHC) of the aquaporins AQP4 and AQP1 was also investigated as these two water channel proteins have been described to play major roles in glioma." (PMID 36077717, 2022). "In this study, we aimed to identify the expression pattern of AQP1 and AQP4 genes in human gliomas, as well as to highlight their regulatory potential within the cancer microenvironment." (PMID 38476871, 2024). "Among the glioma subtypes, AQP1 and AQP4 are overexpressed in astrocytoma (LGG) and classical glioma (GBM)." (PMID 38476871, 2024). "Among the glioma subtypes, AQP1 and AQP4 were overexpressed in astrocytoma (low-grade glioma) and classical (high-grade glioma)." (PMID 38476871, 2024). "In this study, we constructed a novel and highly robust four-gene signature (ACTN1, AQP1, LAMC3, and NRM) based on EMT-related genes to predict grade II/III gliomas prognosis." (PMID 38307919, 2024). "As expected, both AQP1 and AQP4 mRNAs were overexpressed in glioma samples (logFC = 1.42 x 10+14 and 1.02 x 10+14; P-value = 1.66E-40 and 8.82E-26, respectively) compared with the healthy brain samples." (PMID 38476871, 2024). "We used RNA-seq as an experimental strategy and identified the number of differential AQP1 and AQP4 transcript expressions in glioma tissue compared to normal brain tissue." (PMID 38476871, 2024). "Cellular experiments showed ACTN1, AQP1 and NRM promoted glioma cell proliferation, migration and invasion." (PMID 38307919, 2024). "Two members of this family, AQP1 and AQP4, a have a consensus phosphorylation site for PKC, which is a known regulator of glioma cell invasion." (PMID 35847914, 2022).
glioma (continued). "AQP1, AQP4 and AQP9 were reported to be related to angiogenesis, invasion and peritumoral edema in gliomas." (PMID 34712604, 2021). "Moreover, the AQP1 upregulation might also contribute to the angiogenesis in high grade gliomas." (PMID 34712604, 2021). "And AQP subtypes, including AQP1, AQP4 and AQP9, are overexpressed in glioma cells and correlated with tumor grade and malignancy." (PMID 34712604, 2021). "Our histological results were consistent with previous studies that the AQP1, AQP4 and Ki-67 expression were significantly increased in the high-grade gliomas compared with the low-grade gliomas." (PMID 34712604, 2021). "Upregulation of AQP1 and AQP4 protein and RNA has been the major focus of papers published in the glioma field, with additional work identifying possible involvement of AQP9." (PMID 32679804, 2020). "This study demonstrated that IR upregulates AQP1 and AQP4 in GSC glioma tissue and 83NS cells in vitro." (PMID 31803626, 2019). "Targeting the ACTN1, AQP1 and NRM genes may offer new therapeutic opportunities to improve grade II/III gliomas patient outcomes." (PMID 38307919, 2024). "In addition, both AQP1 and AQP4 showed a significant difference in expression pattern upon comparison with tumor markers/antigens in gliomas that are consensually used in clinical practice to establish degrees of malignancy and prognosis." (PMID 38476871, 2024). "The molecular pathways and AQP1 and AQP4 genes identified here may be useful for the molecular diagnosis of gliomas and for screening new anti-tumor drugs for these malignant tumors." (PMID 38476871, 2024). "AQP1 but not AQP4 accelerated migration in glioma cell lines, suggesting that more than water permeability alone was needed for AQP1-facilitated migration." (PMID 35163313, 2022). "In sum, the expression and localization of AQP4 at the leading edges of migrating glioma cells support the idea that AQP4, similar to AQP1, could be a target of interest for novel drug-based GBM treatments." (PMID 34769339, 2021). "In addition, two lesser known genes, AQP1 and MEOX2, are discovered to be prognostic to gliomas patients overall survival through the deep learning approach." (PMID 30626092, 2019). "Gliomas predominantly express carbonic anhydrase 9 (CAIX) and aquaporins 1 and 4 (AQP1 and AQP4)." (PMID 24198789, 2013). "Up-regulations of AQP1 and AQP4 could enhance migration and invasion of glioma cells." (PMID 34712604, 2021). "AQP1 was not expressed in tumor endothelial cells in GSC glioma." (PMID 31803626, 2019). "We used RNA-seq as a search strategy to identify the differential expression of AQP1 and AQP4 transcripts in glioma tissues data compared to normal brain tissues data." (PMID 38476871, 2024). "Expression and transfection studies of AQPs in several commonly used human glioma cell lines suggested that AQP4 enhanced cell adhesion, which was abolished without AQP1." (PMID 35847914, 2022).
melanoma (31 papers, 2009 to 2025). A malignant, usually aggressive tumor composed of atypical, neoplastic melanocytes. "Recently it was shown that AQP1 contributes to cell migration in endothelial and melanoma cell lines via association with Lin7/β catenin." (PMID 20806077, 2010). "AQP1-null mice implanted with melanoma cells showed impaired tumor growth, reduced angiogenesis and decreased cell migration." (PMID 39941100, 2025). "They performed RNA interference knockdown employing AQP1 siRNA on mice implanted subcutaneously with B16F10 murine melanoma cells, revealing aberrant tumour microvascular architecture with lower density." (PMID 38336645, 2024). "Hu and Verkman found that AQP1 accelerates the migration of specific mouse melanoma and breast cancer cell lines in vitro." (PMID 37762642, 2023). "Studies have indicated that AQP1 overexpression in B16F10 melanoma cells and 4T1 mammary gland tumor cells promotes cell migration and lamellipodia formation by enhancing osmotic water permeability across the cell membrane." (PMID 37904849, 2023). "AQP1 overexpression in B16F10 melanoma cells and 4T1 mammary gland tumor cells facilitates cell migration and formation of lamellipodia by increasing membrane osmotic water permeability, allowing sufficient space for actin polymerization." (PMID 35847914, 2022). "By establishing a mouse melanoma model, specific AQP1 siRNAs can effectively reduce the density of tumor microvessels, showing less obvious local tumor invasion and tumor metastasis in in vivo experiments." (PMID 32903818, 2020). "The migration ability of melanoma cells with high expression of AQP-1 was significantly enhanced compared with cells with knockout of AQP-1, as well as local tumor infiltration and metastasis." (PMID 33209198, 2020). "Similar to our findings, this study found that migration was enhanced in AQP‐1‐expressing melanoma cells." (PMID 32253832, 2020). "The importance of AQP1 in tumour angiogenesis was further supported by a study in which a syngeneic melanoma murine model treated with intra-tumoural injection of AQP1 siRNA showed reduced microvessel density." (PMID 31013775, 2019). "Mouse melanoma xenograft model treated with AQP1 siRNA demonstrated decreased microvessel density and increased CASP3 and HIF-1α expression." (PMID 31013775, 2019). "Silencing of the AQP1 gene in a mouse melanoma xenograft model, reduced angiogenesis and metastasis." (PMID 30934923, 2019). "We previously reported that AQP1 silencing by RNA interference reduces angiogenesis‐dependent primary tumour growth in a mouse model of melanoma." (PMID 29044946, 2018). "AQP1 overexpression in B16F10 melanoma cells and 4T1 mammary gland tumor cells enhanced cell migration and lamellipodial width in vitro, and augmented metastasis in a mouse model." (PMID 29922644, 2018). "Saadoun and colleagues observed reduced density of tumour microvessels in AQP1 null mice subcutaneously implanted with melanoma cells, which delayed tumour growth, and prolonged the survival of the mice." (PMID 28146084, 2017). "In human melanoma cells, AQP1 co-immunoprecipitates with several transporters involved in migration and contributes to cell migration through Lin7/beta-catenin interaction." (PMID 25719758, 2015). "This is in line with published observations in malignant melanoma, where increased AQP1 expression also correlated with faster growth." (PMID 25821338, 2015). "Down regulation of AQP1 has been shown to be involved in decreased cell migration in several cell types including human melanoma cell lines, human microvascular endothelial cells, kidney epithelial cells, and gastric epithelial cells." (PMID 20806077, 2010). "Such a role of AQP1 is the same in human melanoma and endothelial cells, suggesting that AQP1 plays a global physiological role." (PMID 19584911, 2009).